CXCR4 (C-X-C motif chemokine receptor 4)
Diseases named in the same sentence as CXCR4 in open-access papers (continued):
Sharing a sentence is not in itself a finding about the gene and the disease.
cancer (continued). "Recent evidence suggests that CXC chemokine receptor 4 (CXCR4) plays a critical role in the homing of cancer cells to specific metastatic sites." (PMID 19580679, 2009). "CXCR4, another member of this family, has recently been shown to be overexpressed in many cancer cell lines." (PMID 19323821, 2009). "Previous reports have shown that CXCR4 expression in cancer cells promotes metastasis to distant organs such as the lung and that CXCR7 expression in cancer cells enhances adhesion onto endothelium under static conditions." (PMID 19484126, 2009). "AMD3100 was able to return adhesion to baseline values at both flow rates, showing that the enhanced adhesion selectivity of circulating cancer cells is due to CXCL12 signaling through CXCR4 on the vascular endothelium." (PMID 19484126, 2009). "Among these chemokines and their receptors, the SDF-1 (also referred to as CXCL12)/CXCR4 system has been shown to be involved in both lymph node and distant metastases of several types of cancer." (PMID 19671192, 2009). "Different types of cancers express different chemokine receptors, however, only the chemokine receptor CXCR4 appears to be expressed by the majority of cancer types." (PMID 19340288, 2009). "Stromal-cell-derived factor-1-α is constitutively expressed in most tissues, whereas CXCR4 is expressed in many cancer cell lines and tissues and is able to mediate the metastasis of a number of cancers." (PMID 19654580, 2009). "The SDF-1/CXCR-4 axis facilitates the directed migration not only of cancer cells but also the bone marrow derived progenitors implicated in the development of the premetastatic niche." (PMID 19383172, 2009). "CXCL12 in normal tissue attracts the CXCR4 on the cancer cells, stimulating cell proliferation and inducing angiogenesis." (PMID 18983683, 2008). "The plasma membrane localization would be compatible with our understanding of CXCR4 function in cancer cell migration and homing." (PMID 19116653, 2008). "Inhibition of the CXCR4-SDF-1-axis by specific CXCR4 antagonists or RNA interference has been shown to block in vitro invasion and in vivo metastasis of cancer cells in animal models." (PMID 19116653, 2008). "Since that time,the CXCL12/CXCR4 axis has been shown to be important in the progression andspread of more than 25 different cancers." (PMID 18779872, 2008). "The involvement of CXCR4 expression incolorectal cancer progression was first shown by Roos and colleagues." (PMID 18779872, 2008). "The CXCR4 protein has multiple essential functions, including homing of stem cells and metastasis of cancer cells." (PMID 18349830, 2008). "Most recently, CXCR4 has shifted into focus as itis the most common chemokine receptor expressed on cancer cells." (PMID 19266088, 2008). "As indicatedabove, the PPARγ agonist rosiglitazone also decreased CXCR4 expression on humancolorectal cancer cells, congruent with an effect of 15dPGJ2 throughPPARγ." (PMID 18779872, 2008). "A cytoplasmatic staining of CXCR4 was observed in all cancers, whereas fewer cases depicted an additionalmembranous localization of CXCR4.These observations are in line with a recently published study byZagzag and coworkers." (PMID 19266088, 2008). "Considering the important role of CXCR4 in cancer progression, we designed a CXCR4 shRNA vector as an alternative to blocking receptor/ligand interaction." (PMID 19002187, 2008). "Recent evidence suggests that metastatic cancer cells overexpress CXC chemokine receptor 4 (CXCR4), and that CXCR4 plays a critical role in homing of cancer cells to specific metastatic sites." (PMID 18826577, 2008). "Recently, it has also been reported that CXCL12 is highly expressed in several internal organs that are the primary targets of cancer cell metastasis, and that CXCR4 is overexpressed on the surfaces of several types of cancer cells." (PMID 19787093, 2008).
cancer (continued). "Since SDF-1 and its receptor CXCR4 (CXC chemokine receptor) system was reported to be correlated with cancer cell migration, SDF-1 was also tested as a chemoattractant." (PMID 18647407, 2008). "Cancer cells that express CXCR4 exploit thesame signaling pathway, leading to homing and retention in tissues that arerich in CXCL12." (PMID 18779872, 2008). "Among the chemokine and chemokine receptors interaction, SDF-1 was proved to be a stimulator of invasion for CXCR4-positive cancer cells." (PMID 19002187, 2008). "Our data showed under normal conditions, the invasive ability of CXCR4-transfected cancer cells was inhibited compared with the control cells." (PMID 19002187, 2008). "Several cancers express CXCR4, and a relationship between CXCR4 expression and malignant potentiality has been suggested." (PMID 18349830, 2008). "In conclusion, our experimental conditions also modified carcinoma cell invasiveness by affecting CXCR4." (PMID 18941460, 2008). "The characterization of the CXCR4/CXCL12 chemokine axis in five UM cell lines have shown significant reduction of cancer cell migration in vitro." (PMID 18001467, 2007). "In conclusion, this study reveals a yet unreported NB-specific predominant growth and survival-promoting role of CXCR4, which warrants a critical reconsideration of the role of CXCR4 in the malignant behaviour of NB and other cancers." (PMID 17925864, 2007). "Both the expression of CXCR4 on cancer cells and CXCL12 on the apical surface of vascular endothelium were examined to assess the role played by chemokines in the anticancer activity of heparinoids." (PMID 17726466, 2007). "In particular, binding of CXCL12 on CXCR4-induced β-integrin expression on cancer cells, which was critical to adhesion of cancer cells to VCAM on endothelial cells." (PMID 16819541, 2006). "The chemokine stromal derived factor-1 (SDF-1/CXCL12) and its receptor CXCR4 have been suggested to regulate organ-specific metastasis in various other cancers." (PMID 17083723, 2006). "More recent studies have suggested that CXCR4 is expressed on various other cancer cells and its expression stimulates migration of cancer cells towards a CXCL12 gradient established in specific target organs." (PMID 17083723, 2006). "Balkwill reviewed that malignant cells from different types of cancer expressed CXCR4 and interact with its ligand SDF-1." (PMID 15978137, 2005). "Recently, it was demonstrated that cancer cells use the stromal cell-derived factor 1 (SDF-1)/chemokine receptor of SDF-1 (CXCR-4) pathway to spread to bone." (PMID 12771933, 2003). "CXCR4 is a key player in cancer biology, regulating crucial biological processes." (PMID 40142263, 2025). "Although not listed by IntOGen for these cohorts, ACVR1 and CXCR4 have been implicated in the tumorigenesis of both cancers." (PMID 40768543, 2025). "For this reason, CXCR4+ cancer cells are attracted to peripheral blood vessels." (PMID 40142155, 2025). "Clearly, this presents significant implications for the timing and combinations of therapy where CXCR4 inhibitors could be advantageous for cancer care by interrupting this self-amplifying loop before it could take root." (PMID 41002447, 2025). "Therefore, this review highlights the biotechnological innovations developed for cancer therapy and diagnosis by targeting the chemokine receptor CXCR4." (PMID 40307933, 2025). "On the other hand, it has been reported that the downregulation of CXCR4 by natural products suppresses the migration and invasion of some cancers, such as liver cancer, confirming the latter hypothesis." (PMID 40142155, 2025). "The detection of CXCR4 oligomers in the cancer cells suggests that they might contribute to cancer development and/or progression." (PMID 41402431, 2025).
cancer (continued). "The first to enter clinical trials was ALX-0651, a biparatopic anti-CXCR4 nanobody for use in cancer therapy that was selected from a library generated from peripheral blood mononuclear cells of llamas that were immunised with HEK293T cells expressing CXCR4." (PMID 39982274, 2025). "ETV4, as a canonical transcription factor, could mediate the development and progression in multiple cancers through transcriptionally regulating its targeted genes, such as Cyclin D1, CXCR4, ANXA2 and KDM5D39-42." (PMID 41281746, 2025). "Similarly, CXCR4 antagonism in synergy with anti-cancer agents has been demonstrated to enhance therapeutic efficacy by inhibiting MDSC recruitment to tumors." (PMID 40822347, 2025). "In addition, CXCR4 is upregulated in many types of cancer, especially on cancer stem cells, and contributes to their survival, proliferation and migration." (PMID 40394646, 2025). "Our results contribute to the theoretical foundation for novel therapeutic strategies that may involve targeting the CXCL12/CXCR4 pathway modulated by CAFs, with the ultimate goal of improving cancer outcomes across species." (PMID 40849508, 2025). "Furthermore, intestinal-type cancer cells that permeated the vascular or lymphatic channels as well as liver and lymph node metastases showed strong CXCR4 and SDF-1 staining." (PMID 40485723, 2025). "CXCR4 is a transmembrane receptor overexpressed in a large variety of cancer cells." (PMID 40395118, 2025). "Consequently, CXCR4 has become a prominent therapeutic target in various cancer types, with ligands including both small-molecule chemical entities and peptides." (PMID 40278256, 2025). "Moreover, CXCR4+ cancer cells show all the characteristics of malignancy, which are high proliferation rate, resistance to conventional therapy, relapse, progression and dissemination from the primary tumor to distant organs." (PMID 40307933, 2025). "Moreover, in IDC paths #1 and #2, marker genes for endothelial cells (VWF and PECAM1), lymphocytes (CD4), macrophages (CD68), chemokines (CXCL12 and CCL5), and chemokine receptors (CXCR4) were expressed highly at the intermediate stages of cancer progression." (PMID 39965034, 2025). "The CXCR4/CXCL12 axis is a crucial mechanism in cancer progression, especially in TNBC." (PMID 41002447, 2025). "FAP+ CAF-induced immune suppression could also be mediated through the CXCL12-CXCR4 axis, and inhibition of CXCR4 resulted in eradication of cancer cells by increasing intratumoral CD8+ T cells." (PMID 39780187, 2025). "The CXCR4/CXCL12 signaling pathway is gaining attention as a promising target for cancer therapy." (PMID 40142155, 2025). "The MMP-1/CXCR4 axis modulates activated fibroblast behavior in both RA and cancer." (PMID 40567613, 2025). "Other CXCR4 inhibitors like plerixafor or balixafortide have already been tested against several types of cancers combined with chemotherapy or cytostatic drugs for improved chemosensitivity and response rates without showing severe side effects linked to bone marrow dysregulation." (PMID 41295054, 2025). "Furthermore the GPCR such as CB1 and CB2 form heterodimers with other GPCR such as HER-2, CXCR4 and others that have implications for cancer progression." (PMID 40109334, 2025). "Peptides represent another class of promising CXCR4 antagonist in cancer therapy." (PMID 40307933, 2025). "Additionally, CXCR4 antagonist AMD3100 has been also incorporated into PLGA nanoparticles for targeted delivery of sorafenib or siRNA molecules into cancer cells." (PMID 40307933, 2025). "The overexpression of the chemokine receptor CXCR4 in cancer cells is primarily regulated by epigenetic mechanisms, including gene hypomethylation in the promoter region and histone acetylation, which is controlled by Histone Acetyltransferases (HATs) and Deacetylases (HDACs)." (PMID 40307933, 2025). "Many GPCRs, including S1PR1 and CXCR4, promote cancer growth and metastasis." (PMID 41100251, 2025).
cancer (continued). "CB2 ligands inhibit migration, invasion and metastasis of CXCR4+ cancer cells." (PMID 40109334, 2025). "CXCR4 is a transmembrane domain heterotrimeric G protein-coupled receptor superfamily member that is expressed functionally on the surface of different kinds of cancer cells." (PMID 40548301, 2025). "Several CXCR4 antagonists are being explored in cancer therapies." (PMID 40943634, 2025). "CXCR4 has a unique ligand known as CXCL12 (also known as stromal-derived factor-1 or SDF-1), which is secreted from multiple stromal components in the TME, such as cancer-associated fibroblasts (CAFs), mesenchymal stem cells and endothelial cells." (PMID 41002447, 2025). "Furthermore, CXCR4 is overexpressed in various cancers, promoting tumor growth, invasion, metastasis, angiogenesis, and therapeutic resistance." (PMID 40012038, 2025). "In addition, GM1-1359 exhibited anti-metastatic activity in bone and sensitized cancer cells to docetaxel more effectively than single treatment with the CXCR4 antagonist CTCE-9980." (PMID 40307933, 2025). "Interestingly, six genes among these (ABCB1, FGF2, CXCR4, IL6, PSMB9, and CLU), as well as UGCG, are known to be highly associated with cancer resistance to platinum-based chemotherapy." (PMID 40507922, 2025). "Furthermore, we investigated two promising molecules AMD3100 and D4476 using synergistic approach for targeting TGFβ-1 and CXCR4 to be explored as better anti-cancer therapeutics in future." (PMID 41348904, 2025). "Furthermore, the CXCR4/CXCL12 axis plays a multifaceted role in cancer, including leukemic stem cell homing and signaling." (PMID 40698080, 2025). "Recent studies have shown, both in vitro and in vivo, that TA exerts antitumor functions by regulating mROS expression or promoting TRAIL-induced extrinsic apoptosis; it is also an inhibitor of CXCL12 (SDF-1alpha)/CXCR4 and decreases cancer stem cell formation (43, –, 45)." (PMID 39692477, 2025). "Co-targeting CXCR4 may inhibit cancer stamens and hypoxia-induced survival signalling and further improve the efficacy of PARP inhibition." (PMID 41002447, 2025). "The transition from healthy tissues subjected to chronic inflammatory noxae to carcinoma involves multiple molecular pathways, including many associated with hypoxic conditions such as hypoxia-inducible factors (HIF), C-X-C motif chemokine receptor 4 (CXCR4), and others." (PMID 40142263, 2025). "Various cancers have shown promising outcomes when CXCR4 inhibitors are used, such as AMD3100." (PMID 39070795, 2024). "To date, several CXCR4 antagonists have been developed for the treatment of these cancers." (PMID 39835121, 2024). "In this state, CXCR4-expressing perivascular TAMs can promote cancer cell intravasation." (PMID 39516356, 2024). "Several antibodies have been developed to target CXCR4 in cancer and other diseases." (PMID 38612911, 2024). "They reported that DPP-4 inhibitors may promote cancer progression via induction of the CXCL12/CXCR4/mTOR axis, which is also important for vascular damage in cancer tissue." (PMID 39135967, 2024). "Consequently, targeting CXCR4 activation through antagonists leads to the egress of hiding cancer cells from bone marrow to the periphery, a process known as chemosensitization, which therefore possesses great therapeutic potential." (PMID 39125877, 2024). "Moreover, correlations between CXCR4 gene expression and metastasis have been unraveled in lung, liver, and bone marrow cancers." (PMID 39715225, 2024). "Targeting CXCR4 also impairs the recruitment of Tregs in murine and human cancers." (PMID 37142825, 2024). "Moreover, the significance of CXCL12 in the TME is explored by its interaction with CXCR4, which is often overexpressed in various cancers." (PMID 39070795, 2024). "Therefore, inhibition of the CXCL12/CXCR4 axis can be a potential therapeutic target in cancers and ADs." (PMID 39070795, 2024). "The activation of CXCL12/CXCR4 axis also plays an important role in the formation of cancer pain." (PMID 39654896, 2024).
cancer (continued). "CXCR4 is expressed across various cell types, including cancer cells and immune cells." (PMID 39545420, 2024). "This phenomenon is attributed to MSCs, pre-adipocytes, and adipose tissue producing and secreting the chemokine CXCL12, which not only facilitates the homing of cancer cells but also, through its receptors CXCR4 and CXCR7, influences gene expression and proliferation in various cancers." (PMID 39518143, 2024). "The upregulation of SDF1 or CXCR4 has been observed to mitigate muscle atrophy and enhance muscle fiber diameter, suggesting that the activation of the CXCR4 pathway could potentially counteract muscle wasting observed in cancer." (PMID 38334644, 2024). "CXCR4-targeted therapies have been proposed for the treatment of cancer metastasis." (PMID 38553476, 2024). "CXCR4-targeted nanoparticles are also under investigation in several cancer types." (PMID 38893721, 2024). "These encouraging results suggest that [68Ga]Ga-TD-01 could be effectively translated into clinical practice for in vivo characterization of CXCR4 expression in GBM and other CXCR4-implicated cancers, with significant potential for improving cancer diagnosis." (PMID 39162901, 2024). "Additionally, SDF-1 and CXCR4 play pivotal roles in regulating cancer cell migration and dissemination." (PMID 39715225, 2024). "More precisely, MIF downregulated the interaction between cancer-associated fibroblasts and immune cells including B cells, DCs, myeloid derived suppressor cells, monocytes, NK cells, and T cells via the CD74/CD44 and CXCR2/CXCR4 signaling pathways." (PMID 38638429, 2024). "Further, CXCR4 expressing CAR-NK cells exhibited an enhanced ability to migrate towards a CCL12 gradient while maintaining functional cytolytic activity towards target cancer cells (CD19+ Nalm-6 cells) in vitro." (PMID 39114657, 2024). "Previously published researches have demonstrated that CXCR4 was overexpressed in GC and affects the proliferation, migration and invasion of cancer cells via the activation of diverse signaling pathways, such as ERK/Akt, NF-kB, JAK2/STAT3, and Wnt/β-catenin pathways." (PMID 38402299, 2024). "CXCR4 is aberrantly overexpressed in several types of cancer, including NSCLC." (PMID 39766230, 2024). "However, there has been no reports on the combination of radiopharmaceutical therapy (RPT) and CXCR4 antagonists in cancer therapy." (PMID 38587644, 2024). "In CAFs, on the other hand, hypomethylation for CpG shore, but not CpG islands, was associated with CXCR4 overexpression, and CXCR4 knockdown suppressed the cancer cell invasion of PDAC cells (Panc1)." (PMID 38892190, 2024). "Therefore, CXCL12-coated cancer cells surrounded by CXCR4-expressing CAFs inhibited both CTL access to the TME and their interaction with malignant cells." (PMID 39596815, 2024). "CXCR4 tends to be aberrantly expressed in many cancer types." (PMID 38612911, 2024). "Importantly, the addition of CXCL12 increases chemotaxis and participates in a positive feedback loop to increase cancer cell expression of CXCR4." (PMID 39766093, 2024). "Also, studies have shown that IFN-γ transforms cancer stem cells into a metastatic form by inducing CXCR4 production and contributing to the microenvironment for cell invasion." (PMID 38543085, 2024). "Moreover, the activity of NF-κB in cancer cells promotes angiogenic pathways by increasing the expression of CXCR4 (C-X-C motif chemokine receptor 4) and CXCL8." (PMID 38418707, 2024). "CXCR4 targeting has been evaluated in treating cancer metastasis and therapy resistance." (PMID 38439632, 2024). "Recognized alternatively as Fusin or CD184, CXCR4 is a type of α-chemokine receptor that spans the outer membrane of many cell types, including lymphocytes, hematopoietic stem cells, epithelial cells, endothelial cells, and cancer cells." (PMID 39715225, 2024). "NPs have been developed using different approaches to enable the use of CXCR4 in cancer therapy." (PMID 39114657, 2024).